RBBP4 (RB binding protein 4, chromatin remodeling factor)
Diseases named in the same sentence as RBBP4 in open-access papers (continued):
Sharing a sentence is not in itself a finding about the gene and the disease.
cervical adenocarcinoma (1 paper, 2025). An adenocarcinoma arising from the cervical epithelium. "Immunohistochemistry was performed on tissue microarrays of lung and cervical adenocarcinoma in order to evaluate RBBP4 expression." (PMID 40187236, 2025).
hepatic (1 paper, 2022). "The expression of Rbbp4, Tcea1, and ILF2 were significantly downregulated in significant hepatic-steatosis NAFLD patients compared to non-significant hepatic-steatosis controls." (PMID 35637971, 2022).
Intellectual disability (1 paper, 2024). "Putative risk variants in RBBP4 have been associated with ASD and intellectual disability." (PMID 39592227, 2024).
Laminopathies (1 paper, 2019). "Laminopathies in general might affect RBBP4/7 levels as shown in the laminopathic disorder HGPS, thereby recapitulating the phenotypes of lin‐53 mutant worms." (PMID 31397537, 2019).
oropharyngeal squamous cell carcinoma (1 paper, 2021). "In addition, RBBP4 was also reported as a significant differently expressed gene between oropharyngeal squamous cell carcinoma patients and patients without cancer in 2009." (PMID 33506032, 2021).
steatosis (1 paper, 2022). Increased lipid within the cytoplasm of cells. "In contrast, overexpression of Tcea1, Rbbp4, and ILF2, respectively, could ameliorate hepatocyte steatosis." (PMID 35637971, 2022).
systemic lupus erythematosus (1 paper, 2024). An autoimmune multi-organ disease typically associated with vasculopathy and autoantibody production. "EFNB1 and RBBP4 enriched in the same items, such as type I diabetes mellitus, systemic lupus erythematosus, hematopoietic cell lineage, etc.." (PMID 39521940, 2024).
tumor (31 papers, 2018 to 2025). "RBBP4 is also implicated in the regulation of DNA repair genes, and its suppression in glioblastoma enhances tumor sensitivity to temozolomide chemotherapy." (PMID 34518534, 2021). "Given the requirement for RBBP4 in neural precursor survival, RBBP4 and its associated chromatin remodeling complexes represent a potential new target to inhibit tumor cells and induce neural cancer cell apoptosis." (PMID 29914980, 2018). "Together, these results identify Rbbp4 and its associated chromatin remodelers as a potential new target for inhibiting tumor cell survival by driving neural cancer stem cells into apoptosis." (PMID 29914980, 2018). "Loss of RBBP4 in GBMs was found to be associated with suppression of tumor growth." (PMID 34086947, 2021). "In the SP2/0 myeloma mice model infected with T. spiralis, genes encoding RpL41, NKTR, Rbbp4, and ANXA2 were enriched in tumor cells, suggesting a potential role in tumor growth inhibition." (PMID 40402283, 2025). "Small interfering RNA (siRNA) downregulated RBBP4 and subsequently inhibited cyclinD1 expression, thereby enhancing cisplatin sensitivity in these tumor cells." (PMID 40187236, 2025). "This study showed that RBBP4 regulates the sensitivity of tumor cells to cisplatin and is a potential target for reversing cisplatin resistance in tumor cells." (PMID 40187236, 2025). "By contrast, the si‐RBBP4 group demonstrated a marked increase in tumor necrosis, accompanied by pronounced nuclear features of condensation and fragmentation." (PMID 39109577, 2024). "At day 21, the tumors were weighed; the average weight was 0.585 ± 0.0342 g in the si‐NC group and 0.28 ± 0.029 g in the si‐RBBP4 group, indicating a significant decrease in tumor weight for the si‐RBBP4 group relative to the si‐NC group (p < 0.01)." (PMID 39109577, 2024). "Together, these results suggest that the tumor suppressor activity of miR-6794-3p is exerted via the ability of RBBP4 inhibition to upregulate GRHL2." (PMID 39430246, 2024). "To explore the roles of both iAR‐DEGs and dAR‐DEGs in the progression of NSCLC, we examined their expression disparities in tumor versus normal samples, and also comparing the distinct RBBP4 expression groups—high and low—in the GSE30219 dataset." (PMID 39109577, 2024). "RBBP4 is a recently discovered protein with tumor-specific characteristics and a molecular weight of 48 kDa." (PMID 38034873, 2023). "One interpretation of this observation is that it reflects the requirement for Rbbp4 in regulation of cell cycle entry as a component of the NuRD complex, which cooperates with the Rb tumor suppressor to block expression of E2F‐regulated early S phase genes." (PMID 35266256, 2022). "Previous work indicated that Rbbp4 cooperates with the Rb tumor suppressor to block cell cycle entry." (PMID 35266256, 2022). "Increased levels of RBBP4 promote tumour growth and mirror the increased nuclear factor κB (NFκΒ) activity in these tumours." (PMID 34073937, 2021). "Analysis of tumor data in TCGA revealed high RBBP4 expression in AML, compared with other tumor types." (PMID 34518534, 2021). "Release of RBBP4 complex occupancy or targeting the interactions between RBBP4 and oncogenic TFs provides increased opportunities for tumor intervention." (PMID 34736517, 2021). "For example, knockdown of RBBP4 in GBM tumor cells results in suppression of the DNA-repair protein Rad51 due to disruption of the RBBP4/p300/CBP chromatin-modifying complex." (PMID 34086947, 2021). "RBBP4 interacts with armadillo repeat-containing 12 (ARMC2) to mediate the repression of tumour suppressor genes in neuroblastoma." (PMID 34073937, 2021). "Our study provides novel insights into the tumor suppressive role of zebrafish Rb1 and its candidate interacting proteins Rbbp4 and Hdac1 in driving persistent tumor growth, and identifies Rbbp4 as a potential target to inhibit tumor cell survival." (PMID 29914980, 2018).
tumor (continued). "ARMC12 physically binds to RBBP4 to increase the PRC2 complex formation and EZH2 activity, leading to repressed gene expression of downstream tumor suppressive targets associated with NB progression." (PMID 30026490, 2018). "RBBP4, a chromatin adaptor for multiple chromatin remodeling complexes, is an E2F target and, as expected, was increased in the zebrafish rb1 tumor and rb1/rb1 homozygous mutant transcriptome." (PMID 29914980, 2018). "Mechanistically, ARMC12 physically interacts with retinoblastoma binding protein 4 (RBBP4) to facilitate the formation and activity of polycomb repressive complex 2, resulting in transcriptional repression of tumor suppressive genes." (PMID 30026490, 2018). "Our finding may open new avenues of research to investigate the potential role of RbBP4–iNOS interaction in either tumor progression or its regression." (PMID 38672406, 2024). "Retinoblastoma binding protein (RbAp48, RBBP4 or NURF55) is a tumor suppressor." (PMID 39076973, 2024). "Taken together, these findings suggest that RBBP4 knockdown may inhibit tumor growth and augment tumor cell apoptosis through enhancement of lethal autophagy." (PMID 39109577, 2024). "Notably, 13 days after multiple siRNA injections, the si‐RBBP4 group exhibited significant suppression of tumor progression compared to the control group (p < 0.05)." (PMID 39109577, 2024). "In addition, RBBP4 contributes to telomere stability in tumor cells and supports their unlimited replication." (PMID 39109577, 2024). "Additionally, RBBP4 overexpression enhances tumor cell radiosensitivity by inhibiting the PI3K/Akt pathway." (PMID 38034873, 2023). "That is why some studies also conclude that RBBP4/7 has an tumor suppressor effect." (PMID 38028543, 2023). "While in yeast and cultured cells, Rbbp4 appears to function as a tumor suppressor with Rb to block cell cycle entry and inhibit cell growth, whether Rb and Rbbp4 interact to regulate the cell cycle in neural progenitors has not previously been examined." (PMID 35266256, 2022). "That means RBBP4 might have influence on the increase of the DNA replication ability and enhance the cell cycle to act as a factor of tumor recurrence." (PMID 33506032, 2021). "Other NuRD members, apart from RBBP4, showed only tumor-specific dependencies." (PMID 32744500, 2020). "Immunohistochemical staining indicated the nuclear RBBP4 expression in tumor cells." (PMID 30026490, 2018). "Therefore, the authors speculated that RBBP4 may affect the sensitivity of tumor cells to cisplatin." (PMID 40187236, 2025). "Furthermore, interfering with RBBP4 expression can significantly inhibit tumor cell growth." (PMID 39109577, 2024). "Therefore, we speculated that RBBP4 could be used as a biomarker or target of platinum resistance or tumor recurrence for subsequent studies." (PMID 33506032, 2021). "Notably, the role of RBBP4 may vary across different tumor types." (PMID 40187236, 2025). "miR-145 can significantly reduce RBBP4 promoter activity, mRNA and protein levels, and hsa_circ_0102231 can promote NSCLC proliferation and invasion by reversing the anti-tumor effects of miR-145 through the miR-145/RBBP4 axis." (PMID 37909018, 2023). "Tumors and normal groups both had high RBBP4 protein levels, and SRM protein levels were moderate in both normal and tumor groups." (PMID 36999051, 2023). "In gastric cancer, RBBP4 is recruited as part of the NuRF complex by the circular RNA circ-DONSON to promote SOX4 expression and produce tumor-promoting effects." (PMID 38028543, 2023). "Previous studies have correlated the overexpression of RBBP4 and RBBP7 with tumor cell proliferation in certain cancer types." (PMID 34086947, 2021). "In neuroblastoma cells, RBBP4 interacts with ARMC12 to facilitate the enrichment of PRC2 and H3K27me3 on tumor suppressive genes such as CADM1, EGLN3 and SMAD9, resulting in transcriptional repression." (PMID 34736517, 2021).
tumor (continued). "RBBP4 expression is higher in triple-negative and HER2-positive tumours in comparison with luminal A and luminal B tumours, correlates positively with HDAC1 expression, and correlates negatively with ER and PR expression." (PMID 34073937, 2021). "To investigate the function of the NuRD complex on the genome level, we performed ChIP-seq assays in RH4 cells for CHD4, RBBP4, HDAC2, and MTA2, as well as for the tumor driver P3F, and other relevant epigenetic regulators and histone marks." (PMID 32744500, 2020). "This study is helpful in extending the knowledge regarding genes crucial for tumor progression, and indicates that ARMC12 and RBBP4 are valuable as potential targets for the treatment of NB." (PMID 30026490, 2018). "Other genes such as RBBP4, DNA2, AP2B1, etc. may also affect tumor immune responses through their respective molecular functions." (PMID 39083127, 2024). "In vivo, targeted siRNA against RBBP4 significantly reduced tumor development in PC9 cell‐injected nude mice, elevating autophagy‐related protein levels and inducing apoptosis and necrosis in tumor tissues." (PMID 39109577, 2024). "We speculate that high RBBP4 expression in NSCLC might inhibit antitumor immune responses, leading to tumor immune evasion and hastening tumor progression." (PMID 39109577, 2024). "We assessed RBBP4 expression using the GSE30219 and TCGA NSCLC datasets and NSCLC cells, exploring its links with clinical outcomes, tumor immunity, and autophagy genes through bioinformatics analysis after transcriptome sequencing of RBBP4‐knockdown and control PC9 cells." (PMID 39109577, 2024). "Furthermore, these high expression levels of RBBP4 and RBBP7 significantly correlated with unfavorable clinical outcomes (P ≤ 0.05) in many tumor types." (PMID 34086947, 2021). "As a nuclear protein, ARMC12 interacts with RBBP4 protein via the ARM domain to increase the formation of PRC2 complex and facilitate the EZH2 activity, which represses the transcription of downstream tumor suppressive genes." (PMID 30026490, 2018). "Furthermore, we analyzed 108 pairs of cancer and adjacent tissues in the TCGA dataset, and the paired t‐test revealed that RBBP4 expression was significantly upregulated in tumor tissues compared to adjacent noncancerous tissues (p < 0.0001)." (PMID 39109577, 2024). "The non-coding RNA KTN1-AS1 binds to HDAC1 via RBBP4 in esophageal cancer to weaken the acetylation of histone H3 (ac-H3) at the promoter region of E-cadherin, thereby activating epithelial mesenchymal transition (EMT), an important process of tumor malignant progression." (PMID 38028543, 2023). "The binding of malignancy factor Sal-like 4 (SALL4) to RBBP4 is similar in that the large and shallow acidic interaction surface of RBBP4 binds to 5 basic residues of SALL4, resulting in the interaction of SALL4 with NuRD and subsequent repression of tumor suppressor transcripts." (PMID 38028543, 2023). "To analyze the RBBP4 and RBBP7 expression levels and correlation with cancer prognosis, we utilized archived patient RNA-seq data from ‘The Cancer Genome Atlas’ (TCGA), focusing on multiple tumor types for which the corresponding normal tissue data were available." (PMID 34086947, 2021).
cancer (29 papers, 2014 to 2025). A tumor composed of atypical neoplastic, often pleomorphic cells that invade other tissues. "The heterogeneous regulatory effects of RBBP4 suggest that its function is closely linked to the genomic and epigenetic contexts of specific cancers." (PMID 40187236, 2025). "This study demonstrates that the expression of RBBP4 is closely associated with the application of cisplatin and is significantly upregulated in the cisplatin-resistant human cancer cell lines A549/DDP and HeLa/DDP." (PMID 40187236, 2025). "This binding is highly conserved in the nucleoplasm, and thus mutations in PHF6 have been studied extensively in the field of cancer, especially leukemia; however, the effects of RBBP4 in mutated PHF6 are still less studied." (PMID 38028543, 2023). "We examined the DepMap database, which encompasses data from genome-wide RNAi and CRISPR loss-of-function screens across hundreds of cancer cell lines, and observed that RBBP4 behaves as a common essential gene." (PMID 34086947, 2021). "Hence, WDR5 demonstrates a stronger association with cancer, in contrast to the broader involvement of RBBP4/7 in various common complexes." (PMID 38028543, 2023). "Interestingly, just as RBBP4/7 is often overlooked in the study of epigenetic complexes implicated in cancer, research on RBBP4/7 in cancer also tends to overlook the complex in which its true functional effects reside." (PMID 38028543, 2023). "Future studies should focus on exploring the regulatory networks and mechanisms of RBBP4 in various tumors to evaluate its clinical applicability in cancer therapy." (PMID 40187236, 2025). "Mounting evidence have shown that RBBP4/7 tends to be upregulated in cancer cells and is closely related to stemness." (PMID 38028543, 2023). "Of note, circ_63706 knockdown downregulated genes contributing to important cancer pathways including RBBP4, TGFA, E2F1, and HRAS." (PMID 36899402, 2023). "This is because low expression of RBBP4 can resist the G2/M phase arrest of cancer cells induced by irradiation and thus become resistant to radiation therapy." (PMID 38028543, 2023). "To assess the potential role of RBBp4 in cancer of HER2+ BC progression due to interaction with SALL4 in HER2+ BC, we analyzed RBBp4 expression in BC patient samples from public databases." (PMID 36362083, 2022). "The retinoblastoma binding protein 4 (RBBp4) is an essential subunit of the NuRD complex, which plays a crucial role in the progression of different cancers." (PMID 36362083, 2022). "According to GSEA analysis, RBBP4 can increase the DNA damage detecting and repairing ability, which can contribute to on-target resistance of the cancer cells." (PMID 33506032, 2021). "The role of RBBP4 in cancer has been explored in the literature, and RBBP4 was found to be a pro-oncogenic factor during gastric carcinogenesis." (PMID 33430870, 2021). "RBBP7, on the other hand, exhibited high selectivity in terms of cancer cell line dependency, reinforcing the concept of orthologue-specific functions for RBBP4 and RBBP7." (PMID 34086947, 2021). "Combined with the DNA damage repair function of RBBP4 and its high expression in cancer, we can infer that it must also play an important role in the resistance of platinum chemotherapy." (PMID 33506032, 2021). "In this review, we summarize the structural characteristics of RBBP4/7, the complexes they are involved in, their roles in embryonic development and cancer, as well as potential future research directions, which we hope to inspire the field of epigenetic research in the future." (PMID 38028543, 2023). "RBBP4 can resist the G2/M phase arrest of cancer cells induced by irradiation." (PMID 38028543, 2023). "The expression of RBBP4 was significantly increased in 13 of the 33 cancer types." (PMID 38034873, 2023).
cancer (continued). "Assuming that we could develop PPI inhibitors based on the binding sites of RBBP4/7, we could further investigate the biological functions of these epigenetic complexes and potentially stimulate novel cancer-targeted therapies." (PMID 38028543, 2023). "This is because metabolic reprogramming in cancer cells or embryo/stem cells is often accompanied by many epigenetic alterations that require a large number of transcriptional regulators, that incidentally drive the upregulation of RBBP4/7." (PMID 38028543, 2023). "This study further discovered that the abundance of RBBP4, G9a, acH3K9 and acH3K18 were changed by metformin treatment, suggesting that there might be a crucial role of histone modifiers for metformin cancer therapy." (PMID 34164906, 2021). "Thus, some researchers believe that RBBP4/7 can be used as a marker for cancer." (PMID 38028543, 2023). "In our cancer model, we found that a high SALL4 expression increases the expression of NuRD complex units, including RBBp4." (PMID 36362083, 2022). "EZH2 combines with EED, SUZ12, and RBBP4 to generate a PRC2 subunit, which is overexpressed in multiple types of cancer." (PMID 36686830, 2022). "Although there has been considerable research focusing on the role of RBBP4/7 in cancer, studies on targeted therapy for RBBP4 are still very sparse, and no successful targeting of RBBP7 has been reported." (PMID 38028543, 2023). "It has been observed that the interaction between SALL4 and RBBp4 may recruit the NuRD complex to the PTEN promoter; as a consequence, PTEN repression and activation of PI3K/AKT pathway are produced, enhancing cancer cell proliferation." (PMID 36362083, 2022). "As such, it is not surprising that RBBP4 and RBBP7 have been extensively implicated in many cancers and are now being pursued as valuable drug targets (reviewd by 24)." (PMID 34086947, 2021). "In addition, in the analysis of prognosis, the high expression of RBBP4 resulted in a reduced survival rate, which also demonstrated its negative effect in cancer recovery." (PMID 33506032, 2021). "However, this does not imply that research on noncatalytic RBBP4/7 in cancer is meaningless." (PMID 38028543, 2023). "Low expression of RBBP4 no longer inhibits E2F1, allowing for increased expression of downstream genes of E2F1 such as OCT4 and SOX2 that maintain cancer cell stemness." (PMID 38028543, 2023).
infection (1 paper, 2016). The state of being infected such as from the introduction of a foreign agent such as serum, vaccine, antigenic substance or organism. "Again, infection with these recombinant viruses resulted in expression of Rbbp4 in infected cells which was confirmed by Western Blot." (PMID 27007137, 2016). "Thus, infection with this mutant should lead to the expression of Rbbp4 in infected cells." (PMID 27007137, 2016).
infectious disease (1 paper, 2025). A disorder directly resulting from the presence and activity of a microbial, viral, or parasitic agent in humans. "In the CAPM group, we identified activation of DDX20- and RBBP4-related infectious disease response pathways, marked by C3 phosphorylation at S715, which is a well-known pro-inflammatory molecule." (PMID 40842862, 2025).